HOXB5 (homeobox B5)
Description:
Sequence-specific transcription factor which is part of a developmental regulatory system that provides cells with specific positional identities on the anterior-posterior axis.
Synonyms: HOX2A; HHO.C10; HOX2; HU-1; Hox2.1
Tractability: PROTAC: ubiquitination databases record sites on it.
Gene: Protein-coding gene on chromosome 17 (48,591,257 to 48,593,779, reverse strand). Ensembl gene ENSG00000120075.
Subcellular location: Nucleus
Subcellular location (Human Protein Atlas): Nucleoplasm; Cytosol; Nucleoli fibrillar center
Gene Ontology:
Molecular function: protein binding; sequence-specific double-stranded DNA binding; DNA-binding transcription factor activity, RNA polymerase II-specific; RNA polymerase II cis-regulatory region sequence-specific DNA binding; DNA binding; DNA-binding transcription activator activity, RNA polymerase II-specific; DNA-binding transcription factor activity
Biological process: anatomical structure morphogenesis; anterior/posterior pattern specification; regulation of transcription by RNA polymerase II; positive regulation of transcription by RNA polymerase II; regulation of DNA-templated transcription
Cellular component: fibrillar center; nucleoplasm; chromatin; nucleus
Genetic constraint (gnomAD): Loss-of-function variants: 9 observed, 17.05 expected, observed/expected ratio (o/e) 0.53, 90% interval 0.32 to 0.92. The upper end of that interval is the gene's LOEUF score, 0.92, which puts it in group 3 of 6, group 1 being the genes least tolerant of losing a copy. Missense variants: 338 observed, 376.9 expected, observed/expected ratio (o/e) 0.9, 90% interval 0.82 to 0.98. Synonymous variants: 160 observed, 164.55 expected, observed/expected ratio (o/e) 0.97, 90% interval 0.85 to 1.11.
Homologues: Orthologues: chimpanzee HOXB5 (100% identical), dog HOXB5 (99% identical), macaque HOXB5 (99% identical), pig HOXB5 (99% identical), mouse Hoxb5 (99% identical), rabbit HOXB5 (99% identical), guinea pig HOXB5 (97% identical), zebrafish hoxb5a (79% identical), zebrafish hoxb5b (71% identical), tropical clawed frog hoxb5 (70% identical). Paralogues in human: HOXA5 (61% identical), HOXB6 (35% identical), HOXD4 (35% identical), HOXC4 (34% identical), HOXA7 (33% identical), HOXB4 (33% identical), HOXA4 (33% identical), HOXC5 (33% identical), HOXB7 (32% identical), HOXA6 (31% identical), HOXD8 (30% identical), HOXB8 (29% identical), and 30 more.
Diseases named in the same sentence as HOXB5 in open-access papers:
HOXB5 is named in the same sentence as 48 diseases in open-access papers, as found by Europe PMC text mining. Sharing a sentence is not in itself a finding about the gene and the disease. The quoted sentences say what the papers report.
breast carcinoma (11 papers, 2011 to 2025). "The expression of HOXB5 is closely associated with the metastasis of colorectal cancer, breast cancer, and hepatocellular carcinoma." (PMID 40642086, 2025). "HOXB5/6 has been associated with an increase in proliferation in breast cancer tissues and cell lines and has been reported to promote the proliferation and migration of pancreatic cancer cells." (PMID 38660676, 2024). "HOXB5 knockdown increases breast cancer cell susceptibility to tamoxifen, whereas overexpression of its expression increases cisplatin resistance in non-small cell lung cancer." (PMID 36443670, 2022). "Previous studies have found that HOXB5 is up-regulated in breast cancer and can enhance tumor growth via the Wnt/β-catenin pathway, and its transcriptional activation of EGFR promotes tumor cell invasion." (PMID 36443670, 2022). "Experimental data suggested that HOXB5 involved in the progression of breast cancer through Wnt/β‐catenin pathway." (PMID 35044082, 2022). "In breast cancer, HOXB5 enhanced cell growth and invasion partly through RET, ERBB2, EGFR, and ESR1." (PMID 34440097, 2021). "HOXB5, a member of the HOX gene cluster, is a key regulator of developmental processes, and it is implicated in multiple human cancers including breast cancer, head and neck cancer, and bladder cancer." (PMID 34497766, 2021). "The tumor-promoting roles of HOXB5 have been found in breast cancer, gastric carcinoma, lung cancer, retinoblastoma, and neck squamous cell carcinoma." (PMID 34497766, 2021).
hepatocellular carcinoma (9 papers, 2018 to 2026). A malignant tumor that arises from hepatocytes. "Three of them (i.e., Pik3cd, Klf4, Hoxb5) were excluded through analysis of their expression in hepatoma cells transfected with the sja-miR-7-5p mimics." (PMID 30967999, 2019). "Further, it was demonstrated that HOXB5 could induce the expression of murine double minute 2 oncogene (MDM2) in hepatoma cells through ERK/MDM2 signaling." (PMID 34617205, 2022). "In hepatocellular carcinoma (HCC), overexpression of HoxB5 transactivates the expression of downstream proteins, fibroblast growth factor receptor (FGFR) 4 and C-X-C motif chemokine ligand (CXCL) 1, leading to enhanced HCC metastasis." (PMID 41535654, 2026). "miR-181a promotes the development of hepatocellular carcinoma by regulating PTEN, CBX7, WIF1, and HOXB5." (PMID 36421826, 2022). "Furthermore, a positive feedback loop involving FGF19, HOXB5, and FGFR4 has been identified in hepatocellular carcinoma, further amplifying oncogenic signaling." (PMID 41584352, 2026).
lung cancer (8 papers, 2009 to 2022). A malignant neoplasm involving the lung. "In pancreatic cancer and lung cancer, HOXB5 promoted cell growth and invasion through β-catenin activation." (PMID 34440097, 2021). "Promoter methylation could be involved in tissue specific silencing of these genes and had been reported for the Hoxa5 gene in lung cancer, in human breast tumors, in myeloid and lymphoid malignancy and for the Hoxb5 gene in ovarian carcinomas where the gene undergoes de novo methylation." (PMID 19812696, 2009). "In lung cancer, it was observed in vitro experiment that proliferation and metastasis of NSCLC cell lines were significantly inhibited when HOXB5 was knocked down." (PMID 35127731, 2021).
ovarian carcinoma (6 papers, 2007 to 2022). A malignant neoplasm originating from the surface ovarian epithelium. "GEPIA analysis demonstrated that HOXB5 was also highly expressed in ovarian cancer tissues and positively correlated with CARD9 according to Spearman correlation." (PMID 36443670, 2022). "The expression of HOXB5 was found to be up-regulated in ovarian cancer, which was consistent with the GEPIA database results, however, there was no research on its effects on the proliferation and metastasis of ovarian cancer cells." (PMID 36443670, 2022). "The major objective of this work was to define the functions of CARD9 and HOXB5 in ovarian cancer cell proliferation, migration, and cisplatin sensitivity." (PMID 36443670, 2022). "Together, CARD9 is involved in ovarian cancer cell proliferation, migration, and cisplatin sensitivity via NF-κB signaling after transcriptional activation by HOXB5." (PMID 36443670, 2022). "In conclusion, this study revealed that CARD9 is involved in ovarian cancer cell proliferation, migration, and cisplatin sensitivity via NF-κB signaling after transcriptional activation by HOXB5." (PMID 36443670, 2022). "This indicated that CARD9 was positively regulated by HOXB5 in ovarian cancer cells." (PMID 36443670, 2022). "Therefore, we explore the roles of CARD9 and HOXB5 in ovarian cancer cells in relation to cisplatin sensitivity." (PMID 36443670, 2022). "Another study has shown that promoter hypermethylation of HOXB5 was observed in ovarian cancer." (PMID 34440097, 2021). "Also, the HOXB5 gene was found to be highly expressed in ovarian cancer and was considered to be an important potential targets in the treatment of ovarian cancer." (PMID 22768238, 2012). "Caspase recruitment domain family member 9 (CARD9) and homeobox B5 (HOXB5) are related and both are upregulated in ovarian cancer." (PMID 36443670, 2022). "CpG island promoter hypermethylation of tumour suppressor genes is a common event in primary ovarian carcinomas and cell lines, and HOXA9, HOXB5, SCGB3A1, and CRABP1, represent novel hypermethylated target genes in this disease." (PMID 17623056, 2007). "APC, CDH13, CRABP1, HOXA9, HOXB5, RASSF1A, and SCGB3A1 were found to be hypermethylated both in the primary tumours and in ovarian cancer cell lines, whereas ADAMTS1 and MGMT were hypermethylated only among cell lines." (PMID 17623056, 2007). "The investigated gene promoters were chosen from loci previously reported to be methylated in ovarian cancer (n = 7; APC, CDH13, MGMT, MLH1, p14ARF, p16INK4a, RASSF1A) and from loci methylated in other tumour types (n = 6; ADAMTS1, CRABP1, HOXA9, HOXB5, NR3C1, SCGB3A1)." (PMID 17623056, 2007).
colorectal cancer (5 papers, 2021 to 2025). A primary or metastatic malignant neoplasm that affects the colon or rectum. "Moreover, HOXB5 is up-regulated in tumors such as endometrial, liver, and colorectal cancers, and participates in tumor cell malignancy." (PMID 36443670, 2022).
bladder cancer (4 papers, 2012 to 2025). "Next, we examined the association between 1010A/G HOXB5 genotype frequency and the clinical features of bladder cancer." (PMID 22768238, 2012). "To investigate the affect of SNP 1010A/G on the expression of HOXB5, we examined the mRNA levels of HOXB5 for the 1010A and 1010G alleles in the heterozygous GA genotype bladder cancer tissues (13 cases) and cell lines (5637, RT4 and J82), using the Taqman assay." (PMID 22768238, 2012). "Genotype frequencies of the HOXB5 polymorphism in bladder cancer subgroups (G1 and G2–G3 groups)." (PMID 22768238, 2012). "A miRNA-binding SNP (1010A/G) located within 3′-UTR of HOXB5 is associated with gene expression and may be a promising prognostic factor for bladder cancer." (PMID 22768238, 2012). "Genotype frequencies of the HOXB5 polymorphism in controls and bladder cancer groups." (PMID 22768238, 2012). "We found that a SNP (1010A/G) within the miR-7 binding site of HOXB5 3′-UTR affects HOXB5 expression and this SNP may be correlated with bladder tumorigenesis and the risk of high grade and high stage human bladder cancers." (PMID 22768238, 2012). "Studies have shown that HOXB5 is frequently overexpressed in bladder cancer tissues and cell lines, and the inhibition of HOXB5 can suppress the carcinogenic function of cancer cells." (PMID 41584451, 2025). "In cell lines, HOXB5 mRNA expression was higher in most bladder cancer cell lines (5637, HT-1376, J82, RT4, T24, and TCCSUP) as compared to normal bladder cell lines." (PMID 37627900, 2023). "RNA was extracted from 35 bladder cancer patients and 8 bladder cancer cell lines and the expression of HOXB5 was measured using qPCR." (PMID 22768238, 2012). "In this study, we showed that the HOXB5 gene was over-expressed and acted as an oncogene in human bladder cancer." (PMID 22768238, 2012). "Here, we showed that the HOXB5 gene was frequently over-expressed in human bladder cancer tissues and in cancer cell lines." (PMID 22768238, 2012). "The expression of HOXB5 was also higher in 6 of 8 bladder cancer cell lines (TCCSUP, 5637, T24, RT4, HT-1376, and J82) than in normal bladder cells." (PMID 22768238, 2012). "Immunohistochemical studies using the HOXB5-specific antibody confirmed that the expression of HOXB5 is higher in bladder cancer tissues than normal bladder tissues." (PMID 22768238, 2012). "We transfected miR-7 to a bladder cancer cell line (5637) with the heterozygous GA genotype for 48 hours and measured the HOXB5 mRNA level using the Taqman assay." (PMID 22768238, 2012). "Expression of HOXB5 in 35 human bladder cancer tissues and 8 cell lines were examined using real-time PCR and immunohistochemistry." (PMID 22768238, 2012). "HOXB5 mRNA was found to be overexpressed in 70% of bladder cancer tissues." (PMID 37627900, 2023). "Moreover, the HOXB5 siRNA-transfected group suppressed clonogenicity in vitro, which further supports the oncogenic function of the HOXB5 in bladder cancer." (PMID 37627900, 2023). "Genotype frequencies of the HOXB5 polymorphism in bladder cancer subgroups (Non-muscle invasive and Muscle-invasive groups)." (PMID 22768238, 2012). "We found that HOXB5 was over-expressed in bladder cancer tissues and in cell lines, indicating that HOXB5 may act as an oncogene." (PMID 22768238, 2012). "We propose that the SNP (1010A/G) may affect the expression of HOXB5 in bladder cancer by differential mRNA stability and binding activity of miR-7." (PMID 22768238, 2012). "HOXB5 was frequently over-expressed both in bladder cancer tissues and cell lines." (PMID 22768238, 2012). "In a pilot study, we found that HOXB5 was frequently over-expressed in human bladder cancer tissues and cell lines, suggesting that it may be a candidate oncogene in bladder cancer." (PMID 22768238, 2012).
bladder cancer (continued). "Next, we demonstrated that a SNP (1010A/G), located within the microRNA-7 binding site in the 3′-UTR of HOXB5, could affect HOXB5 expression in bladder cancer mainly by differential binding activity of microRNA-7 and SNP-related mRNA stability." (PMID 22768238, 2012). "In the present study, we found that HOXB5 was over-expressed in human bladder cancer and our in vitro experiment showed that HOXB5 may act as an oncogene in bladder cancer." (PMID 22768238, 2012). "In summary, in this study we showed for the first time that the HOXB5 gene may act as an oncogene in human bladder cancer." (PMID 22768238, 2012). "Taken together, HOXB5 is overexpressed in bladder cancer and may act as oncogene." (PMID 37627900, 2023). "In vitro experiments showed that HOXB5 may act as an oncogene in human bladder cancer." (PMID 22768238, 2012). "In the present study, we constructed a novel and highly reliable four-gene marker (OAS1, AOC2, HOXB5, and HSH2D) for predicting the prognosis of bladder cancer based on TPECs-related genes." (PMID 41584451, 2025). "Hence, HOXB5 could be a useful prognostic biomarker for bladder cancer." (PMID 37627900, 2023). "Three bladder cancer cell lines (T24, 5637 and TCCSUP) were transfected with an si-HOXB5 or NC duplex, and allowed to grow at very low density (500 cells for T24, 1,000 cells for 5637 and TCCSUP) for about 14 days." (PMID 22768238, 2012). "We examined the half-life of HOXB5 mRNA in the homozygous T24 and TCCSUP bladder cancer cells (GG for T24 and AA for TCCSUP) after treatment with actinomycin D, using qPCR." (PMID 22768238, 2012). "The proliferation and migration abilities of bladder cancer cells were significantly decreased in a HOXB5 siRNA-transfected group as compared to the negative and mock control groups." (PMID 37627900, 2023). "Until now, the biological function of HOXB5 in human bladder cancer has not been reported." (PMID 22768238, 2012).
endometrial cancer (4 papers, 2019 to 2023). Primary or metastatic malignant neoplasm involving the endometrium (mucous membrane that lines the endometrial cavity). "HOXB5 has been shown to be overexpressed in endometrial cancer, and its expression is correlated with tumor stage and poor prognosis." (PMID 37894282, 2023). "The downregulation of HOXB5 by miR-665 is thought to be an important mechanism for regulating the growth and spread of endometrial cancer cells and may have implications for the development of new therapies for this disease." (PMID 37894282, 2023). "One way that HOXB5 may contribute to endometrial cancer is by promoting cell proliferation and survival." (PMID 37894282, 2023). "In endometrial cancer, lncRNA DCST1-AS1 attenuates the inhibitory effect of miR-665 on HOXB5 expression by taking up and reducing the amount of miR-665 and leads to increased HOXB5 levels." (PMID 37894282, 2023). "Also, poor prognosis of patients with endometrial cancer is associated with higher levels of HOXA4, HOX5, HOXA6, HOXA7, and HOXB9 expression, whereas favorable prognosis of patients with endometrial cancer is associated with higher levels of HOXB5 and HOXB6 expression." (PMID 30866492, 2019). "For example, HOXB5 has been shown to activate the PI3K/Akt pathway, which promotes cell survival and growth, and to interact with the estrogen receptor, which is involved in regulating estrogen signaling in endometrial cancer." (PMID 37894282, 2023).